LINC01432 (long independently transcribed non-coding RNA 1432)
Gene: Long non-coding RNA gene on chromosome 20 (22,054,061 to 22,074,657, forward strand). Ensembl gene ENSG00000234435.
Diseases named in the same sentence as LINC01432 in open-access papers:
LINC01432 is named in the same sentence as 3 diseases in open-access papers, as found by Europe PMC text mining. Sharing a sentence is not in itself a finding about the gene and the disease. The quoted sentences say what the papers report.
tumor (1 paper, 2024). "As we are in the earliest stages of understanding LINC01432 tumor biology, this study allows us to predict that LINC01432-CELF2 interaction may play a larger role in the pathogenesis of MM." (PMID 39483883, 2024).
LINC01432 also shares sentences with these, for which no sentence is quoted: androgenetic alopecia (1 paper); cancer (1).